CCDC174 (coiled-coil domain containing 174)
Description:
Probably involved in neuronal development.
Synonyms: C3orf19; FLJ33839; ctr1; HSPC212; IHPM; IHPMR
Tractability: PROTAC: ubiquitination databases record sites on it; its protein half-life has been measured.
Gene: Protein-coding gene on chromosome 3 (14,651,762 to 14,672,659, forward strand). Ensembl gene ENSG00000154781.
Subcellular location: Nucleus
Subcellular location (Human Protein Atlas): Nucleoplasm
Gene Ontology:
Molecular function: protein binding
Cellular component: nucleoplasm; nucleus
Genetic constraint (gnomAD): Loss-of-function variants: 27 observed, 40.22 expected, observed/expected ratio (o/e) 0.67, 90% interval 0.49 to 0.93. The upper end of that interval is the gene's LOEUF score, 0.93, which puts it in group 3 of 6, group 1 being the genes least tolerant of losing a copy. Missense variants: 446 observed, 496.92 expected, observed/expected ratio (o/e) 0.9, 90% interval 0.83 to 0.97. Synonymous variants: 149 observed, 169.01 expected, observed/expected ratio (o/e) 0.88, 90% interval 0.77 to 1.01.
Homologues: Orthologues: chimpanzee CCDC174 (100% identical), macaque CCDC174 (98% identical), dog CCDC174 (91% identical), rat Ccdc174 (86% identical), guinea pig CCDC174 (85% identical), mouse Ccdc174 (85% identical), pig CCDC174 (84% identical), rabbit CCDC174 (84% identical), tropical clawed frog ccdc174 (60% identical), zebrafish ccdc174 (53% identical), Drosophila melanogaster CG7183 (27% identical), Caenorhabditis elegans C37A2.8 (19% identical).
Diseases named in the same sentence as CCDC174 in open-access papers:
CCDC174 is named in the same sentence as 3 diseases in open-access papers, as found by Europe PMC text mining. Sharing a sentence is not in itself a finding about the gene and the disease. The quoted sentences say what the papers report.
abducens nerve palsy (1 paper, 2020). Paralysis of the abducens nerve. "CCDC174 (coiled-coil domain-containing 174) is essential for neuronal differentiation; in human, mutations affect psychomotor developmental delay and abducens nerve palsy." (PMID 32143402, 2020).
female infertility (1 paper, 2026). Diminished or absent ability of a female to achieve conception. "Here, we identified biallelic variants in CCDC174 that cause human oocyte competence defects and female infertility." (PMID 42120494, 2026). "Taken together, our study not only show that CCDC174 is a novel AS regulator that maintains mRNA homeostasis and oocyte competence, but also decipher the critical role of CCDC174 deficiency in the pathogenesis of female infertility." (PMID 42120494, 2026). "Oocyte-specific knockout of Ccdc174 resulted in oocyte maturation arrest and female infertility in mice, and transcriptomic and proteomic analyses indicated that deletion of Ccdc174 disrupted mRNA and protein homeostasis as well as AS in oocytes." (PMID 42120494, 2026).
CCDC174 also shares sentences with these, for which no sentence is quoted: psychomotor developmental delay (1 paper).